KRTAP7-1 (keratin associated protein 7-1)
Description:
In the hair cortex, hair keratin intermediate filaments are embedded in an interfilamentous matrix, consisting of hair keratin-associated proteins (KRTAP), which are essential for the formation of a rigid and resistant hair shaft through their extensive disulfide bond cross-linking with abundant cysteine residues of hair keratins. The matrix proteins include the high-sulfur and high-glycine-tyrosine keratins.
Synonyms: KAP7.1
Tractability: No criterion of Open Targets' tractability assessment is met for any kind of drug.
Gene: Protein-coding gene on chromosome 21 (30,829,039 to 30,829,759, reverse strand). Ensembl gene ENSG00000274749.
Gene Ontology:
Molecular function: protein binding
Genetic constraint (gnomAD): Loss-of-function variants: 2 observed, 3.09 expected, observed/expected ratio (o/e) 0.65, 90% interval 0.26 to 1.71. That is too few expected variants to judge how well the gene tolerates losing a copy. Missense variants: 74 observed, 81.43 expected, observed/expected ratio (o/e) 0.91, 90% interval 0.75 to 1.1. Synonymous variants: 34 observed, 32.8 expected, observed/expected ratio (o/e) 1.04, 90% interval 0.79 to 1.38.
Homologues: Orthologues: chimpanzee KRTAP7-1 (98% identical), dog KRTAP7-1 (89% identical), pig KRTAP7-1 (84% identical), mouse Krtap7-1 (79% identical), rat Krtap7-1 (79% identical), guinea pig KRTAP7-1 (75% identical).